MMP8 (matrix metallopeptidase 8)
Diseases named in the same sentence as MMP8 in open-access papers (continued):
Sharing a sentence is not in itself a finding about the gene and the disease.
coronary artery disease (14 papers, 2007 to 2024). "Plasmatic MMP8 concentrations were linked to the presence and severity of coronary artery disease and serum MMP8 levels were associated with cardiovascular outcome in patients." (PMID 37445827, 2023). "Previous studies reported that circulating MMP-8 is associated with prevalent coronary artery disease, acute coronary syndrome, and future incident CVD events in a general population." (PMID 31752174, 2019). "Similarly, MMP-8 levels were associated with the risk for a coronary artery disease event, MI and death." (PMID 35628490, 2022). "Furthermore, MMP-8 deficiency in ApoE null mice resulted in smaller lesions, and MMP-8 gene variation in patients with coronary artery disease was associated with the extent of coronary atherosclerosis." (PMID 27455234, 2016). "The present findings on circulating MMP-8 may have practical implications on both diagnosis and therapy of carotid and coronary diseases." (PMID 23365489, 2013). "Some authors measured MMP-8 concentrations in 181 patients positive for coronary artery disease (CAD) after angiography and they found that these subjects had higher MMP-8 concentrations, compared with patients without CAD, increasing with the number of stenotic vessels." (PMID 19690642, 2007). "In coronary artery disease (CAD), MMP-8 plasma concentration was found to be increase as the severity of the disease increased." (PMID 39917664, 2024).
lymph node metastasis (14 papers, 2008 to 2026). "Our most intriguing finding is the association of plasma MMP8 levels with lymph node metastasis and the risk of distant metastasis." (PMID 18366705, 2008). "Based on the hypothesis that blood and tissue protein levels are in reverse association, these results suggest that MMP8 in the tumour may have a protective effect against lymph node metastasis." (PMID 18366705, 2008). "Patients with lymph node metastasis (N2) were less likely to have MMP-8-positive PMNs in the tumour and vice versa." (PMID 35328734, 2022). "Our data also showed that the MMP-8 rs11225395 polymorphism related to TNM III+IV stage and lymph node metastasis among CRC patients." (PMID 33052136, 2020). "While the majority of MMPs promote tumor progression, inhibitory roles for MMPs have also been reported, including that of MMP-8 in oral cancer and lymph node metastasis." (PMID 28241871, 2017). "Due to lack of information, the correlation of MMP8 variants with stage and lymph node metastasis in CRC patients has not been explored." (PMID 38031100, 2023). "The absence of tumour-associated MMP-8-positive PMNs was associated with the presence of lymph node metastasis (p = 0.003) as well as perivascular invasion (p = 0.010)." (PMID 35328734, 2022). "In addition, the absence of tumour-associated MMP-8-positive PMNs correlated with lymph node metastasis." (PMID 35328734, 2022). "Based on the hypothesis of reverse association of tissue and blood MMP levels, these results support the anti-metastatic role for MMP8 and may even indicate that MMP8 has a greater protective effect against lymph node metastasis as compared with distant metastasis." (PMID 18366705, 2008). "The median MMP8 levels in controls and lymph node negative patients (pN0) were significantly lower than in patients with moderate lymph node involvement (pN1, pN2); but higher than in patients with extensive lymph node metastasis (pN3) and a strong predisposition to distant metastasis." (PMID 18366705, 2008).
skin cancer (14 papers, 2007 to 2025). "In contrast, the absence of MMP-8 increased susceptibility to chemically induced skin tumours in mice, and bone marrow transplants of MMP-8-expressing neutrophils restored tumour protection." (PMID 33562840, 2021). "Further, germline deletion of MMP-8 in mice increased susceptibility to chemically induced skin tumours, and bone marrow transplants of MMP-8-expressing neutrophils restored tumour protection." (PMID 33037194, 2020). "They found that mice deficient in collagenase-2 (MMP-8) are more susceptible to develop skin cancer and delay in wound healing." (PMID 31379964, 2019). "Recent studies in animal models have shown that mutant mice deficient in MMP8 are more susceptible to develop skin cancer, predicting that MMP8 has a protective function against tumor developments." (PMID 19094243, 2008). "Moreover, germline deletion of MMP‐8 in mice increased susceptibility to chemically induced skin tumors, whereas bone marrow transplants of MMP‐8‐expressing neutrophils restored tumor protection." (PMID 39801760, 2025). "Increased incidence of skin tumours has been observed in MMP-8-deficient mice." (PMID 17311017, 2007). "When the tumor-protective role of MMP8—a novel function for proteases at that time, was first reported in 2003 in breast and skin cancers, it probably increased the interest in the role of MMP8 specifically in those cancers." (PMID 31514474, 2019). "Since it was first reported that MMP-8-/- mice exhibit increased incidence of skin tumours when challenged with chemical carcinogenesis, MMP-8 has been demonstrated to exert a clear tumour-suppressor function." (PMID 28330493, 2017). "In carcinogen-induced skin tumors or in skin wounds there is a delay in neutrophil infiltration at early times in Mmp8-null versus wild-type mice, but this eventually leads to a persistent accumulation at later time points, which exacerbates tumor development and impairs wound repair." (PMID 23632023, 2013). "In skin cancer, immunosuppression does not change MMP8 expression levels or its location, nor did MMP8 expression in skin SCC tumors correlate with its aggressiveness in immunosuppressed transplant patients." (PMID 31514474, 2019). "An increased neutrophil accumulation was found, however, in induced skin carcinomas and during wound healing in mice lacking Mmp8." (PMID 21190566, 2010). "The absence of MMP-8 strongly increases the incidence of skin tumors in these mice." (PMID 35201460, 2021).
Stroke (14 papers, 2011 to 2024). Sudden impairment of blood flow to a part of the brain due to occlusion or rupture of an artery to the brain. "Notably, analysis of 341 DE mRNA associated with stroke (259 upregulated, 82 downregulated) in the IR group revealed upregulation of genes like Ccl2, Cxcl1, C3, Serpine1, Adamts7, Csf3, Ptx3, MMP8, Lif, and Lcn2, and downregulation of Gdf10, Agtr2 and Shank3." (PMID 39170713, 2024). "On days one and seven of stroke, the concentration of IL-1β, MMP-8, OPG and RANKL in the patients’ saliva was assessed using the Elisa technique." (PMID 35893412, 2022). "There was chronic and abundant expression of MMP-2, MMP-3, and MMP-8 in the area of liquefactive necrosis following stroke compared to the equivalent area of infarction in the heart." (PMID 30417081, 2018). "Additional studies examining the role of MMP-1 and MMP-8, and other MMPs in stroke are clearly warranted." (PMID 23565108, 2013). "Our finding also correlates with data from the stroke field, where Cuadrado and colleagues reported upregulation of MMP-8 protein (and other MMPs) in ischemic brain tissue." (PMID 22687332, 2012). "Serum MMP-8 concentrations have been directly associated with risk of future CVD, and the concentrations of MMP-8 and TIMP-1 showed a positive correlation with the severity of stroke." (PMID 39917664, 2024). "Additionally, levels of MMP-8 and MMP-8/TIMP-1 ratio assessed in a cross-sectional study in patients with first IS and in a control group became independently associated with stroke." (PMID 36835040, 2023). "They identified higher macrophage infiltration in carotid plaques, obtained from patients operated early after stroke, compared with asymptomatic patients, as well as significantly elevated levels of a set of proinflammatory cytokines and MMP8, MMP9, and MMP2 activity." (PMID 32206187, 2020). "MMPs can degrade myelin and so the initial high production of MMP-2, MMP-3, and MMP-8 at 24 h following stroke may occur as a microglia/macrophage response to damaged myelin." (PMID 30417081, 2018). "With regard to therapeutic intervention, G-CSF, IL-1β, IP-10, MCP-1, MIP-1α, MIP-1β, RANTES, TNF-α, MMP-2, and MMP-8 were substantially reduced in OPN-/- mice seven weeks following stroke, and these mice exhibited less secondary neurodegeneration in the peri-infarct location." (PMID 30417081, 2018). "Indeed, expression of MMP-2 was 100-fold higher (4273 pg/mg), expression of MMP-3 was almost 3000-fold higher (15,059 pg/mg), and expression of MMP-8 was 500-fold higher (12,923 pg/mg) at eight weeks post stroke in the area of liquefactive necrosis compared to naïve brain tissue." (PMID 30417081, 2018). "In the clinical setting, we previously showed that the circulating levels of neutrophil degranulation products (MMP-8, MMP-9, MPO and NE) peak in stroke patients receiving r-tPA during the first hour after drug administration." (PMID 32977685, 2020). "IL-18 is also present in the area of liquefactive necrosis for at least eight weeks following stroke, and there are also strikingly high levels of MMP-2, MMP-3, and MMP-8." (PMID 30417081, 2018). "These mice also developed birefringent crystals in the infarct in the weeks after stroke and had abundant expression of MMP-2, MMP-3, and MMP-8 in the area of liquefaction seven weeks following stroke." (PMID 30417081, 2018). "The role of other MMPs in stroke are not well described although it also known that MMP-1 (collagenase-1) and MMP-8 (neutrophil collagenase or collagenase-2) are upregulated in the infarcted tissue in human brain compared to healthy control areas." (PMID 23565108, 2013).
asthma (13 papers, 2011 to 2025). "Other authors also showed increased activities of elastinolytic MMP-9 and MMP-13 as well as collagenolytic MMP-8 in equine asthma." (PMID 31316303, 2019). "MMP1, MMP3, MMP8, and MMP12 levels were associated with severe asthma and were correlated positively with sputum IL-5 levels but negatively with IL-13 levels." (PMID 26851968, 2016). "Therefore, corticosteroids may be capable of controlling asthma symptoms, but may be insufficient in preventing the occurrence of airway remodeling involving MMP-8." (PMID 27938355, 2016). "Elevated levels of MMP-1, MMP-2, MMP-8, and MMP-9 have also been found in the sputum and bronchoalveolar lavage fluid of patients with asthma and COPD." (PMID 40940719, 2025). "Before the beginning of inhalation, MMP-8 was higher in asthma of moderate severity, TIMP-1 was lower and the MMP-8/TIMP-1 ratio was higher in mild and moderate asthma in comparison to healthy childeren." (PMID 27938355, 2016). "NETs can also promote secretion of MMP-8 by macrophages in vitro,which is associated with airway obstruction in BALF of human non-controlled severe asthma." (PMID 35911691, 2022).
myocardial infarction (13 papers, 2011 to 2025). Gross necrosis of the myocardium, as a result of interruption of the blood supply to the area, as in coronary thrombosis. "MMP-8 is implicated in the pathogenesis of numerous rheumatologic diseases and has been demonstrated as a biomarker for disease processes ranging from odontogenic inflammation, to left ventricular remodeling after myocardial infarction, to preterm labor." (PMID 22098946, 2011). "Previously, serial samples of ACS patients after myocardial infarction revealed a dynamic quality in the circulating levels of MMP-8, MMP-9, and TIMP-1 in both the acute and the recovery period." (PMID 28278213, 2017). "The level of MMP8 is increased during left ventricular remodelling following myocardial infarction in rats." (PMID 24952741, 2014). "In this study changes in gingival crevicular fluid MMP-8 levels in patients after myocardial infarction were investigated." (PMID 21219642, 2011). "Additionally, doxycycline, an MMP inhibitor independent of its antimicrobial properties, has demonstrated efficacy in reducing MMP7 and MMP8 levels, thereby decreasing the systemic inflammatory burden and potentially preventing secondary myocardial infarctions." (PMID 40136525, 2025). "Plasma MMP-8 levels are increased in patients with atherosclerotic disease, and serum MMP-8 concentration is an independent predictor for myocardial infarction and CAD." (PMID 41026534, 2025). "We found significantly higher MMP-8 concentrations in myocardial infarct patients compared to patients without cardiovascular disease but with a similar periodontal condition." (PMID 21219642, 2011).
pulmonary TB (13 papers, 2015 to 2025). "The follow-up study by the same group with a larger cohort identified 103 DAPs in pulmonary TB vs. latent TB infection, with 9 (including again MMP8) matching our findings and noting the neutrophil-driven inflammation, as we did in our study." (PMID 40981203, 2025). "Neutrophil-associated metalloproteinases MMP8 and MMP9 both mediate matrix destruction during pulmonary TB and contribute to subsequent fibrosis formation." (PMID 36674664, 2023). "Bronchoalveolar lavage fluid (BALF) and plasma from patients with pulmonary tuberculosis contain increased levels of MMP-8 and MMP-947,48." (PMID 35410994, 2022). "We have previously demonstrated that NF-kB inhibition decreased neutrophil MMP-8 secretion which drove type I collagen degradation, a fibril which is important in lung TB but minimally present in the central nervous system." (PMID 28173836, 2017). "In summary, plasma MMP-1 and MMP-8 are elevated in active pulmonary TB, implicating excessive collagenase activity in TB immunopathology." (PMID 25635689, 2015). "To determine the cellular source of MMP-8 in patients with TB, we analyzed lung biopsies from patients who were diagnosed with pulmonary TB." (PMID 25996154, 2015). "The collagenases, MMP-1 and MMP-8, were elevated in plasma of patients with pulmonary TB relative to healthy controls, and MMP-7 (matrilysin) and MMP-9 (gelatinase B) were also increased." (PMID 25635689, 2015). "Neutrophils lined the circumference of human pulmonary TB cavities and sputum MMP-8 concentrations reflected TB radiological and clinical disease severity." (PMID 25996154, 2015). "An increase in MMP-8 and MMP-9 are seen in pulmonary TB and reflects the severity of the destructive process." (PMID 37319185, 2023). "AUC, sensitivity, and specificity values of CXCL1, MMP8, and S100A8 are given for active pulmonary TB (ATB) vs pooled normal, ATB vs latent Mtb infection (LTBI) infection, and ATB vs non-TB comparisons." (PMID 34403447, 2021). "We assume that degradation of this extracellular matrix component by MMP8 in AI lesions might lead to the development of skin cavities (abscesses and draining sinus tracts), as very recently demonstrated for cavities developing in lung tissue during human pulmonary tuberculosis." (PMID 27843200, 2016). "Moreover, neutrophils containing elevated MMP-8 and MMP-9 are localized in the inner wall of cavities, in the central area of necrotic granulomas in patients with pulmonary TB, correlating with matrix destruction." (PMID 37492257, 2023). "Regardless, some, but not all, neutrophil-derived proteins, such as MMP8, could be more universal biomarkers for pulmonary TB." (PMID 40981203, 2025). "Similarly, the results from this study suggest that matrix metalloproteinases (i.e., MMP8 and MMP9) are upregulated in TB sputum vs. non-TB sputum, which is in agreement with previous reported studies that implicated these enzymes in active pulmonary TB." (PMID 40981203, 2025).
emphysema (12 papers, 2005 to 2024). "Evidence for a relevant role in emphysema/COPD development is less established for MMP-8 compared to MMP-12, in particular in the mouse model." (PMID 35031603, 2022). "Increased collagenase activity in lungs of humans with emphysema and bronchiectasis is suspected as a result of MMP-8 activity." (PMID 26770019, 2015). "In smokers with emphysema, MMP-8 and MMP-9 levels in bronchoalveolar lavage (BAL) fluid were significantly higher than in smokers without emphysema." (PMID 23690670, 2013). "Release of MMPs is also crucial for tissue destruction by macrophages in human emphysema and increased activities of MMP-8 and MMP-9 are found in induced sputum of humans with COPD." (PMID 18230187, 2008). "However, elevated levels of MMP-8 could still be observed in elastase-treated mice, suggesting its possible involvement in the maintenance (or even propagation) of the emphysema pathology." (PMID 36611917, 2022). "MMP-8 and MMP-9 are two proteases that are believed to play an important role in the tissue destruction that results in emphysema and both are raised in COPD subjects in the biomarker cohort." (PMID 22054035, 2011). "Elevated protein levels of MMP-1, MMP-8 and MMP-9 were found in BALF or lung parenchyma of patients with emphysema." (PMID 16316467, 2005). "MMP-8 (r = 0.15, p = 0.043), MMP-9 (r = 0.18, p = 0.011) and adiponectin (r = 0.26, p =< 0.001) also correlated weakly with the percentage of emphysema as defined by low attenuation area on chest CT scans; MMP-9 correlated with the radiologists' score of emphysema (r = 0.18, p = 0.010)." (PMID 22054035, 2011).
ovarian carcinoma (12 papers, 2006 to 2025). A malignant neoplasm originating from the surface ovarian epithelium. "The matrix metalloproteinase MMP8 is associated with cancer progression, and IL-1β can induce MMP8 expression in 2780 ovarian cancer cell lines." (PMID 40244135, 2025). "On the contrary to other studies, SNP rs17099462 decreased the expression of MMP8 and was shown to be associated with the increased risk of death from ovarian cancer." (PMID 31514474, 2019). "In ovarian cancer, MMP8 expression has been associated with tumour grade and stage, as well as with poor prognosis." (PMID 18366705, 2008). "The secretion of MMP-8, which has been correlated with ovarian cancer’s overall prognosis, was downregulated by 30%, 16%, and 7% by EGCG, I3C, and Pano, respectively." (PMID 37509102, 2023). "High cytoplasmic levels of MMP8 in ovarian cancer cells correlated to tumor stage and overall poor prognosis, although not strongly enough to be useful as a prognostic marker." (PMID 31514474, 2019). "Therapeutic gold nanoparticles, which decreased ovarian cancer tumor growth and metastasis in vivo, also inhibited ovarian cancer cell proliferation, decreased MMP8 expression, and altered cytokine production in vitro." (PMID 31514474, 2019). "The systematic review on 12 polymorphisms suggested that MMP2 C-735T, MMP7 A-181G, MMP8 rs11225395, MMP9 rs6094237, MMP12 rs2276109, MMP20 rs2292730, MMP20 rs12278250, MMP20 rs9787933 might have a potential effect on ovarian cancer risk." (PMID 28957437, 2017). "Eight polymorphisms (MMP2 C-735T, MMP7 A-181G, MMP8 rs11225395, MMP9 rs6094237, MMP12 rs2276109, MMP20 rs2292730, MMP20 rs12278250, MMP20 rs9787933) were reported associated with ovarian cancer risk, while other polymorphisms could not be associated with ovarian cancer risk." (PMID 28957437, 2017).